SYK (spleen associated tyrosine kinase)
Diseases named in the same sentence as SYK in open-access papers (continued):
Sharing a sentence is not in itself a finding about the gene and the disease.
tumor (continued). "In order to confirm the role of piceatannol targeting to SYK as a tumor suppressor in vitro, we established an in vivo mice model to examine the effect of piceatannol on OSCC tumor growth." (PMID 29137391, 2017). "A tumour metastasis PCR array showed that the expressions of many genes (ECADHERIN, NME4, SYK, CD44 and IL1B) were changed in NPC cells with HOPX overexpression." (PMID 28146149, 2017). "Overall, our results revealed a novel mechanism triggered by SYK to increase OSCC tumoriogenesis and tumor progression." (PMID 29137391, 2017). "FAK signaling has been shown to regulate proteins (e.g. SRC, SYK, FYN, LYN, GRB2, PI3K, and paxillin) that are involved in modulating cytoskeleton rearrangements to enhance tumor growth and metastasis." (PMID 27472394, 2016). "Our work provides mechanistic insights into the actions of cerdulatinib, suggesting that the drug has a broad anti-tumor activity in both ABC and GCB DLBCL, at least in part by inhibiting SYK and JAK pathways." (PMID 26575169, 2015). "In this study, we first demonstrated the presence of active SYK and JAK in their phosphorylated forms in a significant fraction of DLBCL primary tumor tissues and cell lines." (PMID 26575169, 2015). "Interestingly, SYK mRNA loss in postoperative lung metastases was noted although not directly validated post-surgery in an orthotopic mouse model compared with lung metastases of control mice whose primary tumor was not resected." (PMID 24523870, 2014). "SIRPB1 is a member of the signal-regulatory protein (SIRP) family and the activation of this gene is involved in activating the SYK-JAK-STAT signalling, that regulates the proliferation and survival of cancer cells in tumor progression." (PMID 23405089, 2013). "Among them, 10 genes have been reported in HCC, and ZMYND10, SYK, DAB2IP, and DLEC1 have been reported to be tumor-suppressor genes in HCC." (PMID 21625442, 2011). "In our study, functional enrichment analysis of 2160 proteins commonly expressed in 13qCLL/MBL tumor cells identified critical phosphoproteins involved in BCR signaling, immune response regulation, and cell cycle regulation, such as BTK, PRKCB, STAT1, and SYK." (PMID 40129242, 2025). "Given its upstream interaction with SYK and the established downstream activation of PI3K/AKT and NF-κB signaling, it is plausible that FCGR2A may drive tumor progression through these canonical immune-related pathways." (PMID 41208969, 2025). "The SYK is a non-receptor protein tyrosine kinase involved in immune signaling and tumor metastasis initiation." (PMID 40740773, 2025). "Therefore, blocking SYK-induced NETosis is expected to be an effective means to improve liver IRI and reduce tumor recurrence and metastasis of liver tumors." (PMID 39261768, 2024). "In addition spleen tyrosine kinase (SYK) found to be highly expressed in RB tumors and photoreceptor protein recoverin (RCVRN) also expressed in RB were identified as RB tumor cell markers." (PMID 39695086, 2024). "This study aims to investigate the role and mechanism of SYK in hepatic IRI and tumor recurrence." (PMID 39261768, 2024). "Our study demonstrates that neutrophil and macrophage SYK synergistically promote hepatic IRI and tumor recurrence, and SYK may be a potential target to improve postoperative hepatic IRI and tumor recurrence." (PMID 39261768, 2024). "Interestingly, LCK showed a similar pattern of upregulation in DLBCL tumor samples as BTK and SYK, both of which drive the BCR signaling pathway and are therapeutic targets in B-cell malignancies." (PMID 36711753, 2023). "SYK, an important promoter of tumorigenesis in RB, showed a more significant negative correlation between its expression and tumor necrosis." (PMID 36132125, 2022).
tumor (continued). "The results indicated that SYK was heavily expressed (3+) in all tumor cells (82/82), while normal retinas had no expression of SYK." (PMID 36132125, 2022). "In CLL and B-cell non-Hodgkin’s lymphoma (NHL), SYK is involved both in Bruton’s Tyrosine Kinase (BTK) pathway activation and IL4-driven resistance to BTK inhibitors, while JAK kinases transduce cytokine signaling, which supports tumor growth." (PMID 33401428, 2021). "On the other hand, we and others demonstrated that SYK is also expressed in non-hematopoietic cells and that it behaves as a tumor suppressor in mammary epithelial cells." (PMID 33670716, 2021). "In conclusion, small molecule inhibition of the kinase function of SYK does not contribute to a typical tumour suppressor profile." (PMID 32292575, 2020). "Additional support for an involvement of the BCR pathway in the pathogenesis of WM came from observations that a number of BCR signaling molecules, including SFK, SYK, BTK, BLNK, PLCγ2, ERK, AKT, and NF-κΒ, are constitutively activated in primary WM tumor cells." (PMID 32481736, 2020). "Additional evidence for a potential role of the BCR pathway in the pathogenesis of MCL was provided by phospho-proteomic analysis of MCL cell lines and primary tumor samples demonstrating constitutive activation of multiple BCR signaling molecules, including CD79B, LYN, SYK, BLNK, BTK, and PLCγ2." (PMID 32481736, 2020). "The OxLDL-induced and SYK-mediated autophagy facilitates surface expression of MHCII and CD4+ T cells activation; thereby, SYK may enhance anti-tumor immunotherapy effects via a autophagy-mediated adaptive immune responses." (PMID 30678689, 2019). "We re-examined the RNA-Seq data of ccRCC and control samples for SYK transcripts, and found that while SYK was not differentially expressed, it was alternatively spliced in tumors as compared to non-tumor samples in 24 out of 44 (54.5%) studied patients." (PMID 29861861, 2018). "The expression of the TFs from this immune response module is correlated with an increase in the number of Tumour-infiltrating lymphocytes in the TCGA-BRCA dataset and the expression of activated Caspase-7, LCK and SYK proteins indicating an active immune response." (PMID 28588211, 2017). "We then showed that cerdulatinib, a potent inhibitor of SYK and JAK, has broad anti-tumor activity as demonstrated by inhibition of 1) cellular metabolic function, 2) cell viability, 3) cell cycling, 4) signal transduction through SYK-PLCγ2-AKT or ERK, and 5) signal transduction through JAK-STAT." (PMID 26575169, 2015). "Furthermore, treatment with the SYK inhibitor R788 did not affect the tumor cytotoxicity of neutrophils, indicating that SYK-dependent signaling is not essential for this process." (PMID 39590166, 2024). "Notably, in 11 patients with c-Met overexpression but without MET amplification, five SYK-positive patients exhibited significant tumor shrinkage after treatment with c-Metis." (PMID 37183231, 2023). "The mechanisms responsible for activation of the BCR pathway in GCB DLBCL until very recently remained unknown, despite the long-standing evidence that the BCR-proximal kinase SYK is activated in a substantial proportion of GCB DLBCL cell lines and primary GCB DLBCL tumor samples." (PMID 32481736, 2020). "Thus, the SYK inhibitor affects neutrophil production without disturbing their anti-tumor function." (PMID 35453656, 2022). "SYK, a non-receptor tyrosine kinase, has emerged as a key player in EMT, tumor metastasis, and vascular invasion, all of which are hallmark features of aggressive HCC." (PMID 41002582, 2025). "Two patients showed promoter hypermethylation in all four tumour suppressor genes and negative expression of mRNA in RARβ, MGMT and SYK." (PMID 14970867, 2004).
tumor (continued). "The signaling pathways that are activated downstream of the BCR in MZL cells have not been investigated in detail, but analysis of primary tumor samples by phospho-flow cytometry demonstrated constitutive activation of SRC family kinases, SYK, PLCγ2, and p65 NF-κB." (PMID 32481736, 2020). "Furthermore, we compared the presence of SYK protein in MYCN-amplified and non-MYCN-amplified tumor tissue and did not observe differences between the two groups." (PMID 30744170, 2019).
cancer (98 papers, 2010 to 2026). A tumor composed of atypical neoplastic, often pleomorphic cells that invade other tissues. "Tyrosine-protein kinase SYK expression has been associated with the development of various inflammatory diseases, cancer and neurodegenerative conditions." (PMID 38948505, 2023). "The COSMIC database (Cancer Genome Project at the Sanger Institute; an online database of somatically acquired mutations found in human cancer) was assessed for mutations in both SYK and PTEN genes." (PMID 32292575, 2020). "One inhibitor of MEK, PD98059, also suppressed the same cancer-associated phenotypes of SYK-positive cells by decreasing phosphorylated ERK1/2 but increasing phosphorylated mTOR." (PMID 29137391, 2017). "SYK has been associated with cancer in an increasing number of studies, with a dual function." (PMID 29137391, 2017). "Furthermore, evidence suggesting different biological effects for the two known splice variants of SYK on growth properties of cancer cells is accumulating." (PMID 28957395, 2017). "Transcriptomic analysis revealed the upregulation of cell cycle- (MKI67, CCNE2 etc.)and cancer-related genes (SYK, MCM2 etc.), and GSEA confirmed the enrichment of Rb-related pathways." (PMID 41535675, 2026). "In many cancers, SYK promotes cell survival by activating the PI3K/AKT signaling pathway, which stabilizes anti-apoptotic proteins such as MCL-1, BCL-XL, and XIAP." (PMID 40507977, 2025). "We found that cancer cell lines with high SYK expression showed sensitivity to inhibition of both c-Met and EGFR." (PMID 37183231, 2023). "Correspondingly, SYK depletion in MET-amplified cancer cells reduced the G0/G1 cell cycle arrest-induced by c-Meti, while further FRA1 knockdown reversed this reduction." (PMID 37183231, 2023). "Cancer cells with basal levels of SYK expression characterized by visible bands (values ≥ 0.5) were sensitive to all four types of kinase inhibitors, whereas cancer cells with faint bands (values ≤ 0.1) consistently exhibited resistance to these inhibitors." (PMID 37183231, 2023). "Similar results were observed in another two tested models, one model involving MET-amplified MKN45 cancer cells with stable SYK knockdown and one model involving EGFR-mutant PC9 cells with stable SYK knockdown." (PMID 37183231, 2023). "Our earlier studies have identified high-level SYK expression as a likely contributor to cancer drug resistance and relapse in B-ALL." (PMID 36627892, 2022). "Even though lots of studies have indicated that SYK negatively regulates cell proliferation and migration in cancer cells, lots of SYK inhibitors are considered as promising anti-cancer drugs in both clinical studies and pre-clinical studies." (PMID 36568669, 2022). "NCCM from MDA-PATC 148 and BxPC-3 cells pretreated with SYK or PKC inhibitors/collagen I/neutrophil cultures also reduced cancer cell invasion." (PMID 34237033, 2021). "In this study, an in-depth analysis was performed to examine the role and clinical relevance of the SYK gene in CRC development by adopting various cancer databases." (PMID 34575665, 2021). "Recent studies have shown that SYK is highly expressed in multiple cancer cell types and that SYK kinase activity induces cancer cell migration and metastasis." (PMID 34237033, 2021). "First, the differential expression patterns of the SYK gene in various cancer types were analyzed using the Oncomine, GENT2, and GEPIA2 databases." (PMID 34575665, 2021). "For kinase inhibitor-sensitive/resistant diseases, SYK and FLT3/SYK dual inhibitors can increase midostaurin growth inhibition on cancer cells, providing a reliable reference for the clinical combination regimen of midostaurin." (PMID 34976824, 2021). "Both inhibitors can selectively prevent SYK phosphorylation, significantly reduce the infiltration of inflammatory cells and inhibit the progression from liver fibrosis to cancer." (PMID 34853322, 2021).
cancer (continued). "Reduction in SYK expression has been described as a potential prognostic biomarker in several cancers, including HCC." (PMID 32977582, 2020). "Silencing of SYK prevented cancer cell dissemination in vitro and in vivo and pharmacological inhibition of SYK led to a similar decrease in cancer invasiveness." (PMID 31731811, 2019). "Although none of these 20 ncRNAs are targeting FAK or PYK2, most are used to treat cancers, and two are specifically silencing kinases (SYK and PKN3)." (PMID 29891810, 2018). "Integration with publicly available single-cell sequencing data revealed that these proteins were mostly macrophage and monocyte-associated with malignant features (TYMP, FCER1G, FCGR1A, SYK, and F13A1), except NNMT, which was highest in cancer-associated fibroblasts (Table EV4)." (PMID 41233595, 2026). "While CAF-targeted therapies have been proposed in other cancer types, our results suggest that SYK inhibition could disrupt pro-tumorigenic CAF signaling pathways in GBM." (PMID 41463192, 2025). "Additionally, the downregulation of other proteins that have a role in endometrial and other cancers, including SYK, FOXO3A, and cyclin B1, offers insights into the worst survival of the low-muscle/all adiposities group compared to the others." (PMID 39766121, 2024). "Decreased SYK expression with shRNA or TGF-β1 treatment accompanied with increasing FRA1 expression, was associated with an enhanced mesenchymal state and decreased sensitivity of cancer cells to c-Metis." (PMID 37183231, 2023). "We then assessed the association of SYK with the therapeutic response to c-Metis, EGFRis, and other kinase inhibitors for the treatment of NSCLC, such as ALKis and RET inhibitors (RETis), in 15 cancer cell lines." (PMID 37183231, 2023). "The function of SYK in various cancers has been investigated intensively." (PMID 36568669, 2022). "Here, we found that SYK might exert synergistic effects with multiple immune checkpoint molecules and immunogenic cell death modulators across cancers." (PMID 35910221, 2022). "The expression of the SYK gene is equally important for both normal and cancer cells." (PMID 34575665, 2021). "Hence in this system, SYK promoted removal of P-bodies through autophagy and supported activation dormant cancer cells, allowing initiation of cancer metastatic outgrowth." (PMID 33816262, 2021). "Various shreds of evidence suggest that the SYK gene is involved in cancer formation." (PMID 34575665, 2021). "It demonstrates that although some of the SYK targets are shared by many cancer cell types, their protein interactions may be different and thus have a potentially different impact on cell behavior." (PMID 33670716, 2021). "Furthermore, to investigate the functional relevance of the SYK gene in CRC development, the mutations and CNAs of the SYK protein sequence were analyzed based on ten cancer studies." (PMID 34575665, 2021). "Here, the divergent role of SYK in cancer might be due to the phosphorylation or methylation at the promoter region." (PMID 34575665, 2021). "Our study constitutes one of the first demonstrations that lentivirus-targeted immunotherapy may be an effective means for treating cancers and indicates that SYK may prove to be a suitable candidate for targeted therapy of RB." (PMID 29372378, 2018). "Since SYK provides a pro-survival signal and it can modulate tumorigenesis via epithelial-mesenchymal transition, it could serve as a therapeutic target in cancers." (PMID 29719615, 2018). "Moreover, both ERK1/2 and mTOR/S6 signaling were involved in the suppression of proliferation, migration and invasion of cancer cells induced by SYK." (PMID 29137391, 2017). "Because of the correlation of SYK mRNA expression with MSI and a previous study which showed that SYK is differentially expressed in KRAS-dependent and KRAS-independent cancer cell lines, we explored the association between known CRC mutations and SYK expression in our MATCH cohort and TCGA." (PMID 28957395, 2017).